FOXO3 (forkhead box O3)
Diseases named in the same sentence as FOXO3 in open-access papers (continued):
Sharing a sentence is not in itself a finding about the gene and the disease.
tumor (continued). "This implies that the micro-environment, e.g. hypoxic and nutrient-deprived areas within the tumor tissue significantly affects the physiologic outcome of FOXO3-activation in NB tumor cells." (PMID 27769056, 2016). "Foxo3 is a forkhead-box O3 transcription factor that inhibits tumor cell growth and induces apoptosis by activating pro-apoptotic genes." (PMID 27058618, 2016). "To gain more insights into FOXO3 function in NB we analyzed subcellular localization and phosphorylation of FOXO3 at the PKB phosphorylation site T32 in a collection of tumor biopsies from pediatric NB patients." (PMID 27769056, 2016). "This suggests that despite significant reduction of tumor-size, areas of massive extracellular matrix deposition and deletion of a large number of tumor cells, also a significant number of FOXO3-expressing tumor cells persisted." (PMID 27769056, 2016). "The staining of FOXO3 and pFOXO3-T32 revealed both, cytoplasmic and nuclear localization in tumor samples." (PMID 27769056, 2016). "For in vivo experiments, we chose the Balb c nu/nu xenograft mouse model in which we transplanted NB15/Ctr and NB15/FOXO3 tumor cells." (PMID 27769056, 2016). "From the combined data we therefore conclude that FOXO3 in stage IV NB induces tumor vascularization and thereby rather supports tumor growth and metastasis than acts as a tumor suppressor." (PMID 27769056, 2016). "This suggests that FOXO3-activation significantly changed tumor-tissue architecture and reduced tumor cell numbers, but did not completely eliminate proliferating tumor cells." (PMID 27769056, 2016). "Using two different mouse models, we show that FoxO3 has a significant tumour-suppressor function in the context of Myc-driven lymphomagenesis." (PMID 26764572, 2016). "During chemotherapy, hypoxia or nutrient deprivation in the rapidly growing tumor, the majority of tumor cells undergo cell death possibly in part due to strong activation of FOXO3 and in aggressive tumors a selection for aberrant PKB-activation occurs." (PMID 27769056, 2016). "Our results showed that Foxo3 protein level was up-regulated in HepG2 cells in response to ergosterol peroxide treatment, since Foxo3 functions as a tumor suppressor." (PMID 27058618, 2016). "In those animals that underwent 4OHT treatment NB15/FOXO3-derived tumors were significantly reduced in tumor size (P< 0.002), which is consistent with the widely described FOXO3-tumor suppressor function." (PMID 27769056, 2016). "In support of the observation of a reduction in spheroid size, it has been shown that silencing of FOXO3 in HeLa xenografts impaired tumor growth and induced apoptosis." (PMID 28060271, 2016). "Of note, 4OHT-treatment was started when tumors were just palpable at a tumor size when diffusion is sufficient to prevent hypoxic areas within the tumor and therefore FOXO3 mostly acted growth-repressive similar to NB15/FOXO3 cells cultured at normoxia." (PMID 27769056, 2016). "We uncovered that low-level activation of FOXO3 promotes cell growth under hypoxic conditions and tumor angiogenesis in vivo, whereas strong activation reduces tumor size and leads to deposition of extracellular matrix within the tumor tissue." (PMID 27769056, 2016). "In summary, we have demonstrated using two different mouse models that FoxO3 has a significant tumour-suppressor function in the context of Myc-driven lymphomagenesis." (PMID 26764572, 2016). "In this study, we analyzed FOXO3-phosphorylation and cellular localization in tumor biopsies and determined the function of this homeostasis regulator in vitro and in vivo." (PMID 27769056, 2016).
tumor (continued). "In contrast, STA-NB15 cells which were derived from a stage IV NB tumor FOXO3 steady state protein levels as well as phosphorylation on T32 significantly increased during etoposide and doxorubicin treatment." (PMID 27769056, 2016). "It has been identified that the over-expression of Foxo3 inhibited tumor growth in vitro and tumor development in vivo in many cancer." (PMID 26098777, 2015). "FOXO3 is at the interface between longevity and tumor suppression and in skin, its upregulation accounts for the increased susceptibility of cells to UVB." (PMID 25647160, 2015). "The FoxO transcription factor family, including FoxO1, FoxO3 and FoxO4 is reported to act as potent transcription activators and tumor suppressors." (PMID 25503443, 2015). "Similar to all mice, among tumor-free mice, DR appeared to affect lifespan in Foxo3+/− mice differently from that in WT mice (Genotype × Diet, P = 0.0553)." (PMID 25808402, 2015). "In Foxo3+/− mice, DR also significantly decreased the tumor prevalence (P = 0.0263); the prevalence of tumor also appeared to be reduced by DR in Foxo3−/− mice, although it was statistically insignificant probably because of the small numbers of mice examined." (PMID 25808402, 2015). "Single deletion of either Foxo1, Foxo3, or Foxo4 genes resulted in minor alterations in the incidence of neoplasms and lifespan; only triple knockout of Foxo1, Foxo3, and Foxo4 genes caused the cancer-prone phenotype and shortened lifespan." (PMID 25808402, 2015). "In contrast, DR reduced the mortality of tumor-bearing Foxo3+/− and WT mice in a similar fashion (Diet, P = 0.0045; Genotype × Diet, P = 0.3131)." (PMID 25808402, 2015). "Because DR reduced the prevalence of tumors in Foxo3+/− mice, we also analyzed the lifespan data by tumor-free and tumor-bearing mice separately with the Cox proportional hazards model." (PMID 25808402, 2015). "It has been reported that FOXO3 plays a critical role in suppressing tumor growth by increasing cell cycle inhibitor p27kip1." (PMID 25823655, 2015). "In some cases FOXO3 has the opposite effect of enhancing survival of drug-resistant tumor cells through its antioxidant effect like that of FOXO1 in this process." (PMID 24864265, 2014). "This inhibition of function of FOXO3 leads to tumor development and progression, suggesting that FOXO3 is a crucial tumor suppressor." (PMID 25096914, 2014). "Subsequently, βTrCP1, an E3 Ub-ligase, interacts with the FOXO3-pS644 protein and induces the Ub-mediated degradation of FOXO3, resulting in the promotion of tumorigenesis and tumor growth in vivo." (PMID 25096914, 2014). "Since Myc enhances tumor cell proliferation and survival, its downregulation by FOXO3 is antitumorigenic." (PMID 24864265, 2014). "The transcription factor FOXO3 is a well-established tumor suppressor whose activity, stability, and localization are regulated by phosphorylation and acetylation." (PMID 25202904, 2014). "For example, the anticancer drugs such as STI571 and paclitaxel inhibit tumor growth by increasing levels of Bim expression through upregulation of FOXO3 in chronic leukemia cells and breast cancer cells." (PMID 24864265, 2014). "In contrast, in melanoma, miR-182 expression is associated with tumor proliferation and invasion, likely via suppression of the FOXO3 tumor suppressor." (PMID 25329450, 2014). "FOXO3 induces detoxification and stress resistance thereby contributing to tumor stem cell renewal and protection of cancer cells from eradication during chemotherapy and hypoxia." (PMID 23801966, 2013). "The tumor suppressor FoxO3 belongs to a subclass of the forkhead transcription factors, being inhibited by activation of the PI3K pathway." (PMID 22983756, 2013). "Mouse embryonic fibroblasts (MEFs) from Set9 heterozygous and null mice are more susceptible to transformation than wildtype MEFs, suggesting that Set9, like FoxO3, acts as a tumor suppressor." (PMID 22820736, 2012).
tumor (continued). "Overall, independent of MYC, the deacetylation mediated inhibition of several tumor suppressors including FoxO3, Rb, and Ku70, together suggest that SIRT1 has significant tumor promoting activity." (PMID 23024800, 2012). "In humans, inactivation of FoxO3 correlates with poor prognosis in estrogen-dependent breast cancer, illustrating the conserved role of the FoxO family in tumor suppression." (PMID 22820736, 2012). "Since then, several studies have shown direct correlation between FoxO3 expression and tumor progression." (PMID 22489133, 2012). "Treatment of tumor-bearing mice with myriocin significantly decreased expression of Atrogin-1 and Foxo3." (PMID 22257771, 2012). "Collectively, all these studies indicate that FoxO3 is a bonafide tumor suppressor and that deregulation of FoxO3 activity is a major factor in cancer progression." (PMID 22489133, 2012). "Deletion of all FOXO1, FOXO3, and FOXO4 alleles in adult mice induced a cancer prone phenotype, supporting a tumour suppressing function of these proteins." (PMID 22848740, 2012). "In contrast, FoxO3 overexpression inhibited tumor growth in vitro and tumor size in vivo in several cancers such as breast, lymphomas, and hemangiomas." (PMID 22489133, 2012). "The forkhead box transcription factor FOXO3 plays a key role in regulating tumor suppression; however, the control of FOXO3 protein stability remains to be established." (PMID 20625400, 2010). "In animal models, increasing FOXO3 protein level by silencing βTrCP1 suppresses tumorigenesis, whereas decreasing FOXO3 by over-expressing βTrCP1 promotes tumorigenesis and tumor growth in vivo." (PMID 20625400, 2010). "Here we show that βTrCP1 is a key E3 Ub-ligase that regulates the protein degradation of FOXO3 tumor suppressor." (PMID 20625400, 2010). "FOXO3 has been identified as both an oncogenic gene and a tumor suppressor." (PMID 40308216, 2025). "Consequently, the tumor-suppressive role of FOXO3 is substantiated by its ability to increase the levels of these miRNAs, ultimately resulting in the repression of the oncogenic factors VEGF-A and NRP1." (PMID 40003882, 2025). "Of note, previous studies have established the tumor-suppressive role of FOXO3 in various cancers." (PMID 40589632, 2025). "In addition, GlcN increases the expression of FoxO1 and FoxO3, which play a crucial role as tumor suppressors in various cancers." (PMID 39816727, 2025). "GlcN also increased the expression of FoxO1 and FoxO3, known tumor suppressors in various cancers." (PMID 39816727, 2025). "FOXO3 is a tumor suppressor and crucial regulator of the Wnt/β-catenin signaling pathway." (PMID 40136629, 2025). "Interestingly, SIRT1 and FOXO3 have been shown to play critical roles in various types of cancer, typically influencing tumor progression by regulating cell growth, apoptosis, and autophagy." (PMID 39266959, 2024). "The immunohistochemical results demonstrated that the administration of CAPE could enhance the phosphorylation of AMPK in tumor tissues and facilitate the nuclear translocation of Foxo3." (PMID 39729481, 2024). "The AMPK/FOXO3 signaling pathway is known to have tumor-suppressive properties." (PMID 39334758, 2024). "Interestingly, LINC01714 enhanced gemcitabine sensitivity of CCA tumor cells by regulating FOXO3 phosphorylation." (PMID 38725864, 2024). "In MYC‐driven lymphomagenesis, FOXO3 had a remarkable tumour‐suppressor function." (PMID 37987202, 2024). "Another novel drug, Syringaresinol, which targets FOXO3, has anti-tumor and antioxidant activities." (PMID 39221148, 2024). "Similar to FOXO1, most studies agree on the tumor-suppressive feature of FOXO3." (PMID 37821870, 2023). "However, miR-1307 is involved in tumor development by influencing target genes, such as Forkhead box O3a (FOXO3A), SET And MYND Domain Containing 4 (SMYD4) and Disabled homolog 2-interacting protein (DAB2IP), to further promote cancer invasion." (PMID 37889117, 2023).
tumor (continued). "Among the key players, Forkhead box O3a (FOXO3a) acts as a tumor suppressor." (PMID 38068934, 2023). "A tumor suppressor gene, Foxo3 protein is downregulated in various tumors." (PMID 37400900, 2023). "Strikingly and in contrast with FOXO3, which displayed tumour suppressor activity (p = 0.0069), FOXO1 was ranked second (p = 2.41 × 10−8) in the list of essential genes, a finding consistent with previous observations that inhibition or knock-down of FOXO1 negatively affects B-ALL growth." (PMID 36670235, 2023). "Collectively, these data indicated that FOXO3 played a tumor-suppressive role in UBC." (PMID 37573356, 2023). "For example, Foxo3 gene is downregulated in many tumors and is considered as a tumor suppressor." (PMID 37060016, 2023). "The expression of circ-Foxo3 was analyzed in tumor cells both in 2D monolayer and 3D multilayer." (PMID 37400900, 2023). "Overexpression of FOXO3 in UBC cells abrogated tumor cell proliferation and migration." (PMID 37573356, 2023). "Taken together, these data suggest FOXO1 and FOXO3 harbour tumour suppressive qualities in MM." (PMID 37275916, 2023). "Similarly, immune/inflammation-related TFs, such as NFKB2, STAT1, and RELA, and FOXO3, showed high activity in CXCL10+MEL and TMSB4X+MEL subclusters, which underlies the immunomodulatory phenotype of tumor cells." (PMID 38065972, 2023). "Moreover, the ratio of phosphorylated FOXO3 (p-FOXO3) to total FOXO3 is related to tumor grade, and in low-grade UBC, a decreased p-FOXO3/FOXO3 ratio suggests a lower recurrence risk." (PMID 37573356, 2023). "Silencing of Foxo3 in pDCs partially restores their stimulatory function in a mouse tumor model." (PMID 37781382, 2023). "Thus, FOXO3 has been proposed to be a regulator that is intrinsically involved in tumor immunity, homeostasis, and immunocytes growth, including T cells, NK cells, and DCs." (PMID 36900213, 2023). "In AFPGC, miR-122-5p suppressed apoptosis and accelerated tumor growth via targeting Forkhead box O3 (FOXO3), suggesting that miR-122-5p may be a potential therapeutic target in AFPGC." (PMID 36803831, 2023). "Moreover, venetoclax (BCL2i)-resistant FL cells exhibit increased levels of p-FOXO1/p-FOXO3 associated with diminished BIM activity, thereby preventing cell death supporting the role of FOXO family members as tumour suppressors in FL." (PMID 37275916, 2023). "Mechanistically, miR-29a-3p functioned as a tumor-promoting factor by downregulating the FOXO3-AKT/GSK3β axis and subsequently suppressing the expression of PD-L1, which was a known target molecule for anti-tumor immunotherapy, to shield OC cells from immune escape." (PMID 36355327, 2023). "In this study, we confirmed that FOXO3 was a tumor suppressor in UBC." (PMID 37573356, 2023). "In addition, our results demonstrated that the transcription of RASIP1 was negatively regulated by FOXO3, which has been reported as an anti-tumor factor in multiple cancer cells." (PMID 36967521, 2023). "Additionally, dysregulation of FOXO3 has been identified to result in accelerated tumor formation and disease progression in TRAMP mice." (PMID 37174744, 2023). "Furthermore, the anti-tumor effects were also reported in AOM/DSS-induced CRC in high-fat mice through the PI3K/AKT/FOXO3 or SIRT1/FOXO3 signal cascades." (PMID 37298531, 2023). "Its inhibition leads to tumor development and progression, suggesting that FOXO3 reactivation could be a promising strategy to develop anticancer therapeutic drugs." (PMID 34850406, 2022). "FOXO3 is commonly regarded as a tumor-suppressive gene in cancer." (PMID 34795388, 2022). "ROC assays revealed that FOXO3 could be used to distinguish HCC tissues from non-tumor tissues with an AUC of 0.7878 (p < 0.001)." (PMID 33654226, 2022).
tumor (continued). "By eliminating METTL3-mediated FOXO3 mRNA stabilization in the hypoxic tumor microenvironment, METTL3 depletion significantly enhanced the drug resistance of HCC to sorafenib, which confirmed FOXO3 as a crucial m6A modification downstream molecule in the sorafenib resistance of HCC." (PMID 36517820, 2022). "In HCC, FOXO3 has been reported to be distinctly upregulated and promote tumor progression." (PMID 33654226, 2022). "FOXO3 has been reported as a crucial transcriptional factor involved in tumor suppression." (PMID 35941699, 2022). "Silencing of circ‐Foxo3 could increase cell viability, whereas overexpression of circ‐Foxo3 could induce apoptosis and suppress tumour growth." (PMID 33277969, 2022). "Additionally, previous studies have demonstrated that FOXO3 promoted the invasion and migration of tumor cells by inducing an MMP expression." (PMID 36555288, 2022). "Considering the tumor-suppressive roles of FOXO3 in various cancers, we hypothesized that autophagy could regulate CSC properties by degrading FOXO3." (PMID 34795388, 2022). "However, there exists a conflict between the tumour suppressive or oncogenic role of the FOXO3 gene, based on its nuclear or cytoplasmic localization and its phosphorylation at different residues by respective interacting partners." (PMID 36727057, 2022). "In NIH3T3 cells, SIRT1 causes ubiquitination and degradation of FOXO3, a FOXO transcription factor family member that can play a crucial role in tumor suppression and metabolism and may act as oncogene." (PMID 35136826, 2022). "Additionally, we proved for the first time that regorafenib exerts its anti-tumor actions in chemoresistant HCC by impairing such cytoprotective FOXO3 upregulation and autophagy induction." (PMID 34769197, 2021). "Moreover, RBPJ-OE Mφ-Exos inhibits tumor growth by stimulating the LBX1-AS1/miR-182-5p/FOXO3 pathway in vitro and in vivo." (PMID 33816238, 2021). "Emerging studies have demonstrated that circRNAs, especially circ-Foxo3, could play a role as tumor promoters or tumor suppressors in various human cancers via diverse regulatory mechanisms." (PMID 33833780, 2021). "Furthermore, FOXO3 protein level was downregulated in the tumor xenografts with stable LINC01124 knockdown." (PMID 37304672, 2021). "Meanwhile, it has been suggested that deregulation of FOXO3 expression or activity could provoke tumor development and boost the apparition of more aggressive tumor phenotypes such as those with chemoresistance." (PMID 34769197, 2021). "Foxo3 protein is downregulated in many tumors and is considered a tumor suppressor gene." (PMID 34202482, 2021). "Notably, Afuresertib treatment induced the clear nuclear accumulation of FOXO3 in the PDX tumor cells, and the Ki67 labeling indices of tumor cells decreased significantly." (PMID 33795838, 2021). "Therefore, both of FOXO1 and FOXO3 proteins are well-known tumor suppressive transcriptional factors involved in many kinds of cellular functions, such as cell cycle arrest and apoptosis." (PMID 34745413, 2021). "This feature showed the potential of circ-Foxo3 in tumor suppressive activity." (PMID 33833780, 2021). "However, there are opposing reports about the role of FOXO3 expression in cancer, finding that FOXO3 upregulation can act either as a tumor-suppressive or an oncogenic mechanism, depending on the tumor type or specific circumstances." (PMID 34771514, 2021). "In summary, LINC01124 plays a tumor-promoting role in HCC by regulating the miR-1247-5p–FOXO3 axis." (PMID 37304672, 2021). "Furthermore, Tam treatment significantly suppressed the organoid development of Gan Foxo3+/Act and Gan Foxo3Act/Act tumor cells when organoids were enzymatically dissociated to single cells and passaged." (PMID 33795838, 2021). "FOXO-3 genes act as tumor suppressors by promoting cell cycle arrest and apoptosis." (PMID 34743742, 2021). "In summary, Met inhibits tumor growth partially depend on FOXO3." (PMID 34546972, 2021).